SORL1 (sortilin related receptor 1)
Description:
Sorting receptor that directs several proteins to their correct location within the cell (Probable). Along with AP-1 complex, involved Golgi apparatus - endosome sorting. Sorting receptor for APP, regulating its intracellular trafficking and processing into amyloidogenic-beta peptides. Retains APP in the trans-Golgi network, hence preventing its transit through late endosomes where amyloid beta peptides Abeta40 and Abeta42 are generated. May also sort newly produced amyloid-beta peptides to lysosomes for catabolism. Does not affect APP trafficking from the endoplasmic reticulum to Golgi compartments. Sorting receptor for the BDNF receptor NTRK2/TRKB that facilitates NTRK2 trafficking between synaptic plasma membranes, postsynaptic densities and cell soma, hence positively regulates BDNF signaling by controlling the intracellular location of its receptor. Sorting receptor for GDNF that promotes GDNF regulated, but not constitutive secretion. Sorting receptor for the GDNF-GFRA1 complex, directing it from the cell surface to endosomes. GDNF is then targeted to lysosomes and degraded, while its receptor GFRA1 recycles back to the cell membrane, resulting in a GDNF clearance pathway. The SORL1-GFRA1 complex further targets RET for endocytosis, but not for degradation, affecting GDNF-induced neurotrophic activities. Sorting receptor for ERBB2/HER2. Regulates ERBB2 subcellular distribution by promoting its recycling after internalization from endosomes back to the plasma membrane, hence stimulating phosphoinositide 3-kinase (PI3K)-dependent ERBB2 signaling. In ERBB2-dependent cancer cells, promotes cell proliferation. Sorting receptor for lipoprotein lipase LPL. Promotes LPL localization to endosomes and later to the lysosomes, leading to degradation of newly synthesized LPL. Potential sorting receptor for APOA5, inducing APOA5 internalization to early endosomes, then to late endosomes, wherefrom a portion is sent to lysosomes and degradation, another portion is sorted to the trans-Golgi network. Sorting receptor for the insulin receptor INSR. Promotes recycling of internalized INSR via the Golgi apparatus back to the cell surface, thereby preventing lysosomal INSR catabolism, increasing INSR cell surface expression and strengthening insulin signal reception in adipose tissue. Does not affect INSR internalization. Plays a role in renal ion homeostasis, controlling the phospho-regulation of SLC12A1/NKCC2 by STK39/SPAK kinase and PPP3CB/calcineurin A beta phosphatase, possibly through intracellular sorting of STK39 and PPP3CB (By similarity). Stimulates, via the N-terminal ectodomain, the proliferation and migration of smooth muscle cells, possibly by increasing cell surface expression of the urokinase receptor uPAR/PLAUR. This may promote extracellular matrix proteolysis and hence facilitate cell migration. By acting on the migration of intimal smooth muscle cells, may accelerate intimal thickening following vascular injury. Promotes adhesion of monocytes. Stimulates proliferation and migration of monocytes/macrophages (By similarity). Through its action on intimal smooth muscle cells and macrophages, may accelerate intimal thickening and macrophage foam cell formation in the process of atherosclerosis (By similarity). Regulates hypoxia-enhanced adhesion of hematopoietic stem and progenitor cells to the bone marrow stromal cells via a PLAUR-mediated pathway. This function is mediated by the N-terminal ectodomain. Metabolic regulator, which functions to maintain the adequate balance between lipid storage and oxidation in response to changing environmental conditions, such as temperature and diet. The N-terminal ectodomain negatively regulates adipose tissue energy expenditure, acting through the inhibition the BMP/Smad pathway (By similarity). Sorting receptor that may regulate signaling by the heterodimeric neurotrophic cytokine CLCF1-CRLF1 bound to the CNTFR receptor by promoting the endocytosis of the tripartite complex CLCF1-CRLF1-CNTFR and lysosomal degradation. May regulate IL6 signaling, decreasing cis signaling, possibly by interfering with IL6-binding to membrane-bound IL6R, while up-regulating trans signaling via soluble IL6R.
Synonyms: LR11; SorLA; C11orf32; gp250; LRP9; SorLA-1
Tractability: Antibody: UniProt places it where antibodies can reach, with high confidence; its Gene Ontology location is reachable by antibodies, with high confidence; UniProt predicts a signal peptide or a membrane-spanning region. PROTAC: ubiquitination databases record sites on it; its protein half-life has been measured.
Gene: Protein-coding gene on chromosome 11 (121,452,314 to 121,633,763, forward strand). Ensembl gene ENSG00000137642.
Subcellular location: Golgi apparatus membrane; Golgi apparatus, trans-Golgi network membrane; Endosome membrane; Early endosome membrane; Recycling endosome membrane; Endoplasmic reticulum membrane; Endosome, multivesicular body membrane; Cell membrane; Cytoplasmic vesicle, secretory vesicle membrane; Secreted
Pathways (Reactome):
Metabolism of proteins: Amyloid fiber formation
Gene Ontology:
Molecular function: amyloid-beta binding; aspartic-type endopeptidase inhibitor activity; cargo receptor activity; low-density lipoprotein particle binding; neuropeptide binding; protein binding; protein transporter activity; small GTPase binding; low-density lipoprotein particle receptor activity; transmembrane signaling receptor activity
Biological process: insulin receptor recycling; lysosomal protein catabolic process; negative regulation of amyloid precursor protein catabolic process; negative regulation of amyloid-beta formation; negative regulation of cytokine-mediated signaling pathway; negative regulation of protein-containing complex assembly; neuropeptide signaling pathway; positive regulation of adipose tissue development; positive regulation of endocytic recycling; positive regulation of ER to Golgi vesicle-mediated transport; positive regulation of glial cell-derived neurotrophic factor production; positive regulation of insulin receptor signaling pathway; positive regulation of protein catabolic process; positive regulation of protein localization to early endosome; post-Golgi vesicle-mediated transport; protein localization to Golgi apparatus; protein retention in Golgi apparatus; protein targeting; protein targeting to lysosome; receptor-mediated endocytosis; regulation of smooth muscle cell migration; retrograde transport, endosome to Golgi; adaptive thermogenesis; diet induced thermogenesis; negative regulation of BMP signaling pathway; and 5 more
Cellular component: cell surface; early endosome; early endosome membrane; endoplasmic reticulum; endoplasmic reticulum membrane; endosome; endosome membrane; extracellular exosome; extracellular region; Golgi apparatus; Golgi cisterna; Golgi membrane; membrane; multivesicular body; nuclear envelope lumen; plasma membrane; recycling endosome; recycling endosome membrane; trans-Golgi network; cytosol; lysosome; multivesicular body membrane; neuronal cell body; perinucleolar compartment; transport vesicle membrane
Genetic constraint (gnomAD): Loss-of-function variants: 105 observed, 226.64 expected, observed/expected ratio (o/e) 0.46, 90% interval 0.4 to 0.55. The upper end of that interval is the gene's LOEUF score, 0.55, which puts it in group 2 of 6, group 1 being the genes least tolerant of losing a copy. Missense variants: 2,233 observed, 2,632.4 expected, observed/expected ratio (o/e) 0.85, 90% interval 0.82 to 0.88. Synonymous variants: 938 observed, 1,007.1 expected, observed/expected ratio (o/e) 0.93, 90% interval 0.88 to 0.98.
Homologues: Orthologues: chimpanzee SORL1 (99% identical), macaque SORL1 (98% identical), guinea pig SORL1 (95% identical), rabbit SORL1 (94% identical), mouse Sorl1 (93% identical), rat Sorl1 (93% identical), dog SORL1 (93% identical), pig SORL1 (92% identical), tropical clawed frog sorl1 (71% identical), zebrafish sorl1 (64% identical). Paralogues in human: SORCS3 (12% identical), SORCS1 (12% identical), SORCS2 (12% identical), SORT1 (11% identical).
Diseases named in the same sentence as SORL1 in open-access papers:
SORL1 is named in the same sentence as 101 diseases in open-access papers, as found by Europe PMC text mining. Sharing a sentence is not in itself a finding about the gene and the disease. The quoted sentences say what the papers report.
Alzheimer disease (105 papers, 2006 to 2026). A progressive, neurodegenerative disease characterized by loss of function and death of nerve cells in several areas of the brain leading to loss of cognitive function such as memory and language. "Sorting protein‐related receptor containing class A repeats (SORLA) is an intracellular trafficking receptor encoded by the Alzheimer's disease (AD) gene SORL1 (sortilin‐related receptor 1)." (PMID 39688327, 2025). "Protein truncating variants (PTVs) in SORL1 are observed almost exclusively in Alzheimer’s Disease (AD) cases, but the effect of rare SORL1 missense variants is unclear." (PMID 41327266, 2025). "Genetic, clinical and functional analyses strongly support involvement of the sortilin-related receptor 1 (SORL1, which encodes SORLA) in Alzheimer’s disease." (PMID 38576795, 2024). "Regional brain expression of several Alzheimer-risk genes, including APOE, CD33, and SORL1, showed a strong correlation with brain metabolism, particularly in regions of the brain that are affected earliest and most severely in Alzheimer’s disease." (PMID 38469573, 2024). "Sodium and hyperpolarized [1-13C]pyruvate MRI offer a window into the metabolic consequences of SORL1-associated Alzheimer’s disease and the temporal changes during the development of disease." (PMID 38650831, 2024). "The endosomal gene SORL1 is a strong Alzheimer's disease (AD) risk gene that harbours loss-of-function variants causative for developing AD." (PMID 38368935, 2024). "SORL1 (1.36-fold) encodes for a sorting protein-related receptor that is downregulated in Alzheimer’s disease (AD) and is implicated in the trafficking and processing of amyloid precursor protein (APP)." (PMID 39335533, 2024). "The SORL1 gene has a long history for its association with Alzheimer's disease; this was initiated in 2007 when a candidate gene approach identified several single nucleotide polymorphisms (SNPs) in SORL1 that were associated with sporadic and late-onset AD." (PMID 38368933, 2024). "Sortilin-related receptor 1 (SORL1) is an intracellular sorting receptor genetically implicated in Alzheimer’s disease (AD) that impacts amyloid precursor protein trafficking." (PMID 38657864, 2024). "Aged TBI also have significant activation of upstream cytokines including TGFB, as well as the endosomal trafficking and risk factor for Alzheimer’s disease gene SORL1." (PMID 37588516, 2023). "All three of the replicated genes have been previously associated with clinically diagnosed Alzheimer’s disease (SORL1, TREM2, and TOMM40/APOE)." (PMID 36750708, 2023). "SORL1 is also involved in retromer-related endosomal trafficking and is a risk gene for Alzheimer's disease." (PMID 37205232, 2023). "For example, differences in SORL1 gene alleles, and its encoded protein, which has a role in iron homeostasis, have been linked with Alzheimer’s disease." (PMID 37998376, 2023). "SNPs cause conformational shifts from G-quadruplex to hairpin structures in pre-miRNA 1229, thereby increasing the level of mature miRNA 1229 and subsequently the translation of the sortilin-related receptor 1 (SORL1) gene, causing Alzheimer’s diseases." (PMID 36360167, 2022). "The present study evaluated the risk effect of 12 Single Nucleotide Polymorphisms in the SORL1 gene in the Mexican population using Late-Onset Alzheimer’s Disease (LOAD) and control subjects." (PMID 35456392, 2022). "It is important to note that five proteins with evidence of interaction are involved in the processing and clearance pathway of amyloid-beta peptides and have previously been associated with Alzheimer’s disease, including the SORL1 protein, S5A Fig." (PMID 35905044, 2022). "Sortilin Related Receptor 1 (SORL1) is a protein-coding gene that is currently known to be most closely associated with Alzheimer’s disease." (PMID 35464477, 2022). "Loss of the Sortilin-related receptor 1 (SORL1) gene seems to act as a causal event for Alzheimer’s disease (AD)." (PMID 35226190, 2022).
Alzheimer disease (continued). "Genetic analysis revealed an association of SORL1 with both sporadic and familial forms of Alzheimer’s disease (AD)." (PMID 35183222, 2022). "In the last few years, the SORL1 gene has been strongly implicated in the development of Alzheimer’s disease (AD)." (PMID 35457051, 2022). "The sortilin-related receptor 1 gene (SORL1) encodes a key protein (SORLA) involved in the pathophysiology of Alzheimer disease (AD)." (PMID 33879716, 2021). "In conclusion, by assessing missense variants located throughout the coding sequence of the SORL1 gene among rare variants found in Alzheimer disease patients, we identified a novel mechanism leading to a loss of SorLA function." (PMID 34922638, 2021). "They indicated that miR-1229, by targeting SORL1, which are both expressed in the human brain, can cause Alzheimer’s disease." (PMID 33841080, 2021). "The SorLA protein, encoded by the SORL1 gene, is a major player in Alzheimer’s disease (AD) pathophysiology." (PMID 34922638, 2021). "SORL1 processes a causal involvement in Alzheimer’s disease (AD) as a proposed modulator of the amyloid precursor protein (APP)." (PMID 31092209, 2019). "These include various scavenging receptors implicated in Alzheimer’s disease pathogenesis that were increased with age and reversed by microglial repopulation (e.g., A2m, Apoe, Olr1, Sorl1)." (PMID 30477578, 2018). "Using three different patient cohorts of early onset Alzheimer disease, we describe three SORL1 variants that segregate with disease in three families adding to the literature which supports SORL1 as a major player in AD pathoetiology." (PMID 28595629, 2017). "Apolipoprotein E (APOE) and sortilin-related receptor (SORL1) genes act on the same metabolic pathway and have been associated with Alzheimer’s disease (AD) characterized by hippocampal impairment." (PMID 28229235, 2017). "The sortilin-related receptor 1 (SORL1) gene has been associated with increased risk for Alzheimer’s disease (AD)." (PMID 27026413, 2016). "Support for SORL1 as an Alzheimer's disease risk gene has been mixed, but a recent meta-analysis of previous studies detected a significant association between clusters of polymorphisms in SORL1 and Alzheimer's disease in both Caucasians and Asians." (PMID 24278680, 2012). "The genetic association of SORL1 with Alzheimer’s disease has been well established." (PMID 41493977, 2026). "Variants of SORL1 have been associated with both late and early onset of Alzheimer’s disease (AD)." (PMID 40551140, 2025). "Finally, we demonstrate that the N1358S mutant of SORL1 significantly increases tau seeding when compared to WT SORL1, identifying for the first time a potential mechanism that connects this specific SORL1 mutation to Alzheimer’s disease." (PMID 38657864, 2024). "While SORLA loss-of-function variants occur almost exclusively in Alzheimer's disease cases, the majority of SORL1 variants are missense variants that are individually rare and can have individual mechanisms how they impair SORLA function as well as have individual effect size on disease risk." (PMID 38368933, 2024). "The SORL1 gene has recently emerged as a strong Alzheimer’s Disease (AD) risk gene." (PMID 38244079, 2024). "Of note, SORL1 has been associated both genetically and experimentally with Alzheimer’s disease, and the expression of its transcript was upregulated within the olfactory bulb of patients with early Alzheimer’s disease activity, perhaps as a compensatory mechanism." (PMID 37998376, 2023). "SORL1 mutations, occurring frequently in a subset of familial cases of Alzheimer’s disease (AD), have been documented, but their pathogenic potential is not yet clear and questions remain concerning their putative influence on the physiopathological processing of APP." (PMID 38132122, 2023).